TMPRSS2 (transmembrane serine protease 2)
Diseases named in the same sentence as TMPRSS2 in open-access papers (continued):
Sharing a sentence is not in itself a finding about the gene and the disease.
viral infection (continued). "TMPRSS2 inhibitors and cathepsin inhibitors reduce virus infection with different efficacy, indicating that both entry routes are active and cooperate." (PMID 38002267, 2023). "In relation to TMPRSS2, we focused on rs2070788 which was suggested with interest on virus infections, in combination with other SNPs in present gene." (PMID 37287057, 2023). "Current research has revealed that TMPRSS2 inhibitors are superior to endocytosis inhibitors at preventing viral infection in human primary nasal epithelium." (PMID 37196033, 2023). "In contrast to its physiological role, the involvement of TMPRSS2 in viral infection has been extensively investigated." (PMID 35163273, 2022). "Here, we analyzed three polymorphisms of the human TMPRSS2 and CCR5 genes to highlight possible associations between alleles/genotypes and resistance/sensitivity to viral infection or different symptoms related to COVID-19 disease." (PMID 36012436, 2022). "Taken together, our analyses uncover strong cell type-specific host factor requirements, with expression of TMPRSS2 playing a major differentiating role to determine which pathways are important for viral infection." (PMID 35879412, 2022). "If the cathepsin-mediated endocytosis pathway can also be used for SARS-CoV-2 infection in Calu-3 cells, then a certain level of viral infection should be observed even when TMPRSS2 activity is inhibited by nafamostat." (PMID 36243815, 2022). "Although the physiological aspect of TMPRSS2 remains incomprehensible, it certainly plays an essential role in viral infection by priming and activating SARS-CoV-2 S proteins." (PMID 35632833, 2022). "Endothelial cells express SARS-CoV-2 targets for cell entry, angiotensin-converting enzyme 2 (ACE2) receptor, and transmembrane serine protease 2 (TMPRSS2), allowing for direct viral infection of endothelial cells." (PMID 35389890, 2022). "A recent study reported that the SARS-CoV-2 S protein is activated under acidic conditions by the endolysosome proteases TMPRSS-2 and cathepsins B and L, so deacidification of this organelle has been shown to deactivate proteases and suppress viral infection." (PMID 35456026, 2022). "Genome-wide CRISPR knockout and activation screens in human lung epithelial cells with endogenous expression of the SARS-CoV-2 entry factors ACE2 and TMPRSS2 identify mucins as key host factors restricting viral infection." (PMID 35879412, 2022). "MG decreased SARS-CoV-2 spike pseudotyped virus infection in the ACE2/TMPRSS2-overexpressing HEK293T cells, as confirmed by decreased GFP fluorescence." (PMID 36235822, 2022). "From eight candidates, the authors identified N-0385 as the most potent inhibitor of TMPRSS2 and viral infection in vitro." (PMID 35871159, 2022). "Subsequently, we investigated the role of three enzymes, furin, TMPRSS2, and cathepsin L, during viral infection." (PMID 34818119, 2022). "This process is similar to that observed for SARS‐CoV‐183, 84, 85 and validated by the TMPRSS2 inhibitor camostat, which inhibits virus infection of TMPRSS2‐positive cells." (PMID 35599305, 2022). "The second possibility refers to differences between males and females in the expression levels and genetic variants in angiotensin-converting enzyme 2 (ACE2) receptor and cellular serine protease TMPRSS2, the two crucial genes for viral infection." (PMID 35712238, 2022). "Altogether, these data suggest that both male and female sex-related hormones are able to induce a proteolityc activation of TMPRSS2, thus promoting viral infection, in agreement with the observation that males and females are equally infected by SARS-CoV-2." (PMID 35712238, 2022). "Of note, A549 cells lack expression of TMPRSS2, making cathepsin glycoprotein processing and endosomal entry likely pathways in viral infection." (PMID 35421191, 2022).
viral infection (continued). "To examine if the knockdown of ACE2 prevents viral infection, we decided to use high (Huh-7) and low (Vero E6) TMPRSS2 expressing cell lines for analyzing potential effects of the entry pathways on the efficacy of siRNA-mediated inhibition." (PMID 35309990, 2022). "Another advantage to target TMPRSS2 is its activating function in other viral infections (e.g., other coronaviruses, influenza virus), which expands the field of potential applications for TMPRSS2 inhibitors." (PMID 35871159, 2022). "Herein, we discuss the physiological role of the transmembrane protease serine subtype 2 (TMPRSS2) and its utilization as an entry cofactor in viral infection and a target for antiviral agents." (PMID 35163273, 2022). "Cell lines overexpressing ACE2 and furin, TMPRSS2, or cathepsin L (CatL) proteins were used to study the effects of these three enzymes on viral infection." (PMID 34818119, 2022). "An attractive drugtarget is the human transmembrane protease serine 2 (TMPRSS2) becauseof its vital role in the viral infection mechanism of SARS-CoV-2 byactivation of the virus spike protein (S protein)." (PMID 35549216, 2022). "The results suggested that although the introduced mutations are near the theoretical cleavage site of TMPRSS2, they have little effect on the promotion of virus infection by TMPRSS2 in 293T-ACE2 cells." (PMID 34856891, 2022). "Nevertheless, in the present study, the GSEA results revealed that TMPRSS2 was associated with influenza A, herpes simplex virus 1 infection and Epstein–Barr virus infection, indicating that TMPRSS2 indeed plays a role in viral infection." (PMID 35017320, 2022). "The differences in angiotensin converting enzyme 2 and transmembrane serine protease 2 regulation and immune response to viral infections between males and females are emerging as the potential mechanisms." (PMID 34280188, 2021). "It is possible that PARP1 reactivates the transcription of TMPRSS2 during viral infection, however further research is needed to make any statement." (PMID 34445373, 2021). "A priming step of virus infection is represented by the cleavage of S protein by the transmembrane serine protease 2 (TMPRSS2)." (PMID 34281186, 2021). "The experiments with virus infection in vitro provide a proof of principle that A1AT not only biochemically inhibits TMPRSS2 but also possesses the ability to inhibit SARS-CoV-2 infection." (PMID 33969249, 2021). "We also investigated virus infection of a variety of lung lines that endogenously express TMPRSS2, AXL, and ACE2." (PMID 34797899, 2021). "We show that primary human endothelial cells express very low levels of the SARS‐CoV‐2 receptor ACE2 and the protease TMPRSS2, which blocks their capacity for productive viral infection, and limits their capacity to produce infectious virus." (PMID 34721846, 2021). "We also examined the changes in mRNA level of ACE2 and TMPRSS2 by the viral infection combined with 24 h of fluoxetine (10 μM), clomipramine (10 μM), and chlorpromazine (5 μM) treatment." (PMID 35126106, 2021). "Transfection of 10 ng of TMPRSS2 plasmid enhanced virus infection at low concentrations of ACE2, but virus entry became TMPRSS2-independent at higher levels of ACE2 in a manner similar to the effects of the PS receptors." (PMID 34797899, 2021). "The experiments using pseudotyped viruses to infect HEK293T cells overexpressing ACE2 and TMPRSS2 were aimed at identifying the direct effect of drugs on the entry phase of the viral infection, as we added the virus and drugs around the same time." (PMID 35126106, 2021). "Given that honeysuckle-EtOH reduced protein binding and cell fusion, we also evaluated the expression of two key cellular factors, ACE2 and TMPRSS2, required for viral infection by western blot assay." (PMID 35401158, 2021). "The inhibition of TMPRSS2 has been shown to prevent the viral infection of severe acute respiratory syndrome coronavirus 2 (SARS-CoV-2) and other viruses." (PMID 33996911, 2021).
viral infection (continued). "It is possible that IRF1 binding in the upstream region of TMPRSS2 plays a pivotal role in the induction of this gene transcription during viral infection." (PMID 34445373, 2021). "The cellular protease TMPRSS2 primes the S protein and promotes the transmission during the viral infection, and the inhibitor of TMPRSS2 blocks the SARS-CoV-2 infection of lung cells." (PMID 33401657, 2021). "Recent research has confirmed that SARS-CoV-2 entry is facilitated by TMPRSS2 and the viral infection is decreased by the use of the protease inhibitor camostat." (PMID 34222852, 2021). "In the present review, we will highlight the recent updates on the functional role of host proteases, specially TMPRSS2 and furin in viral infection and discuss the possible interventions for inhibiting these enzymes." (PMID 34527703, 2021). "During viral infection, when the S protein binds to the receptor, transmembrane protease serine 2 (TMPRSS2), a type 2 TM serine protease located on the host cell membrane, activates the S protein by cleaving it into S1 and S2 subunits." (PMID 34073047, 2021). "In preparation for testing the viral respiratory infection model with coronaviruses, we probed for transcript and protein expression of cell surface proteins ACE2 and TMPRSS2, known to play central roles in facilitating viral infection by SARS-CoV-241." (PMID 34294757, 2021). "Some conditions such as obesity were observed to be responsible for the expression level of TMPRSS2, thus influencing the rate of the viral infection." (PMID 34336361, 2021). "The inability of the S gene mutants to use TMPRSS2 for S protein activation presumably hampers efficient viral infection and dissemination in airway epithelial cells." (PMID 34425707, 2021). "Along with this timeline, the specific process within human cells is also frequently studied as presented in community #5 gene expression, where ACE2 and TMPRSS2, two of the key genes involved in the viral infection process, are highlighted." (PMID 34109284, 2021). "Another membrane protein pivotal to viral entry in the cell is TMPRSS2, shown in our interactome and down-regulated by viral infection." (PMID 32244779, 2020). "Among the hPSC-derived lung cells, alveolar type II and ciliated cells are the major cell populations expressing the viral receptor ACE2 and co-effector TMPRSS2, and both were highly permissive to viral infection." (PMID 32839764, 2020). "The proteolytic cleavage of Spike protein by TMPRSS2 results in the shedding of S1 domain, which is one of the key steps of the virus infection in host cells." (PMID 33329480, 2020). "It was shown that TMPRSS2 inhibition (by protease inhibitor or in TMPRSS2 knock-out mice) prevented viral entry and reduced the viral infection and severity of lung pathology with improved survival after SARS-CoV infection in mouse models." (PMID 33228225, 2020). "Furin, TMPRSS2, and cathepsin L enzymes are also important for the early stage of the viral infection." (PMID 32993173, 2020). "Specifically, FGFR1 inhibition enhances the interferon (IFN) response to viral infection, whereas blocking neddylation reduces levels of TMPRSS2 (transmembrane protease serine 2), which is needed for the cleavage of SARS-CoV-2 spike protein to initiate infection." (PMID 41585476, 2026). "Given its substantial role in viral protein activation, including hormonal modulation, and its association with other proteases that may alter cell sensitivity to viral infections, TMPRSS2 is a viable therapeutic target." (PMID 40297833, 2025). "Inhibition of TMPRSS2 activity has emerged as a viable strategy to impede viral infection." (PMID 40145441, 2025). "TMPRSS2 and other TTSPs as well are important drug targets in viral infections and various cancers." (PMID 41408854, 2025).
viral infection (continued). "As investigations into the intricate interplay between TMPRSS2 and viral infections continue, a comprehensive understanding of its multifaceted functions holds promise for the development of innovative therapeutic strategies and a more nuanced approach to managing viral respiratory diseases." (PMID 39858469, 2025). "As a result, studying TMPRSS2 methods of action and subcellular location provides insights into designing effective antiviral therapies, establishing it as a key target for therapeutic intervention toward viral infections." (PMID 40297833, 2025). "This link is significant as it indicates that addressing TMPRSS2 might successfully disrupt the early phases of viral infection." (PMID 40297833, 2025). "Notably, patients with these malignancies are identified as a significant risk group due to their heightened susceptibility to viral contagion, underscoring the complex interplay between TMPRSS2, viral infections, and cancer." (PMID 39858469, 2025). "Modulation of TMPRSS2 expression increased or decreased the sensibility to viral infections." (PMID 38185627, 2024). "This makes it an attractive target for COVID-19 treatments, as inhibiting TMPRSS2 function could prevent or reduce viral infection." (PMID 39003338, 2024). "Lactoferrin may also defend against viral infection in females by lowering ACE2 together with the low expression of TMPRSS2 which are necessary for SARS-CoV-2 entry in the cells." (PMID 38836262, 2024). "We also quantified plaque size upon viral infection in Vero and VeroE6/TMPRSS2 cells." (PMID 38332154, 2024). "Furthermore, TMPRSS2 knockout mice showed a reduced/delayed immune response towards the immunostimulant poly I:C that resembles a double-stranded RNA and simulates viral infections." (PMID 36830955, 2023). "Therefore, Transmembrane serine protease 2 (TMPRSS2) is an essential target in combating SARS-CoV-2 as it plays a significant role in viral infection and cell entry." (PMID 37809955, 2023). "It would be intriguing to investigate whether TMPRSS2 can bind to the surface proteins of other TMPRSS2-dependent viruses, potentially establishing a broader role for the Spike-binding domain in viral infection." (PMID 37896901, 2023). "Furthermore, another study has shown that α-5 reductase inhibitors, another class of androgen inhibitors decreasing the amounts of DHT in cells and inhibiting the AR signaling, reduced TMPRSS2 expression and viral infection in lung organoids." (PMID 36834705, 2023). "This underscores the importance of a comprehensive understanding of the interplay between tyrosine kinases and TMPRSS2, which could pave the way for innovative treatment strategies targeting both viral infections and cancer." (PMID 37896901, 2023). "Most studies focus on TMPRSS2 function in disease conditions, like cancer or viral infection." (PMID 36830955, 2023). "Thus, a primary viral infection in the eyes would require the ocular surface to be a site of protein expression in the viral binding sites (ACE2/TMPRSS2)." (PMID 36851565, 2023). "Moreover, minor importance of the serine protease TMPRSS2 for viral infection of AB8 podocytes in cell culture experiments was demonstrated." (PMID 36979408, 2023). "Due to the positive correlation of TRIM31 with TMPRSS2 and TMPRSS4 genes, it may therefore cause higher susceptibility of viral infections, such as SARS-CoV-2, seen in cancer patients." (PMID 35970857, 2022). "We examined the expression of ACE2 and TMPRSS2 in an induced usual interstitial pneumonia (iUIP) mouse model and patients with IPF as well as the changes in whole-lung ACE2 and TMPRSS2 expression under physiological conditions caused by viral infection." (PMID 36405683, 2022). "Additionally, as the FCS region has been suggested to play an important role in TMPRSS2-mediated viral infection and fusion between the virus and its target cells, we tested the effects of TMPRSS2 host protease in pseudovirus infection." (PMID 35458533, 2022).
viral infection (continued). "Furthermore, transmembrane protease serine 4 (TMPRSS4) is reported to activate SARS-CoV-2 S proteins along with TMPRSS2, and enable viral infection of the human small intestine." (PMID 35632833, 2022). "It is possible that PARP1 reactivates the transcription of TMPRSS2 during viral infection." (PMID 35162972, 2022). "Furthermore, the AUC-ROC values for TMPRSS2 rs12329760 were 0.708, indicating that host genetic variables frequently contribute to viral infection mortality." (PMID 36457338, 2022). "Moreover, we did not perform our assays in a clinically relevant cells, where viral infection is dependent on TMPRSS2 and supports membrane fusion to facilitate syncytium formation." (PMID 35458533, 2022). "Therefore, the TMPRSS2 KO condition in these mice specifically suppresses virus infection dependent on TMPRSS2 expression." (PMID 36243815, 2022). "Indeed, we demonstrate that H2S-releasing donors significantly reduce the expression of the protease TMPRSS2 on epithelial cells from upper (nasal) and lower (bronco/alveolar) airways, potentially limiting viral infection." (PMID 34572459, 2021). "Since the TMPRSS2 is involved in other viral infections such as coronavirus (MERS-CoV, SARS-CoV, hCoV-EMC, and HCoV-229E), hepatitis C virus, and influenza A virus, it would be an attractive alternative against a wide spectrum of respiratory viruses, especially SARS-CoV-2." (PMID 34527703, 2021). "Primary SARS-CoV-2 respiratory infection induces systemic inflammation (CXCL10, IFN-ɤ, IL-1B, IL-6, IL-8, IL-17, TNF-α) that can impact the musculoskeletal system through the expression of hACE2-R and TMPRSS2 genes in various types of musculoskeletal cells, allowing direct viral infection." (PMID 33919537, 2021). "Another investigation reported that coexpression of ACE2, TMPRSS2, and mitochondrial genes could make cornea a potential and important contributor for the viral infection." (PMID 34336361, 2021). "AAT suppresses the key protease TMPRSS2 and inhibits viral infection." (PMID 34066804, 2021). "Moreover, as a viral infection is enhanced by TMPRSS2, the Vero E6 cell line overexpressing TMPRSS2 has been described as a useful pharmacological tool for SARS CoV-2 research." (PMID 34222852, 2021). "In addition, the ingredients found in this study (SDS, TDS, LMT, LSS, GCU, and TXA) have been shown to inhibit the serine protease activity of TMPRSS2, which is involved in the viral infection of cells after ACE2 and spike protein binding." (PMID 34534255, 2021). "Additionally, most studies evaluated the risk of viral infection by examining the expression of ACE2 and TMPRSS2, which is sort of arbitrary, because other co-receptors promote the entry of SARS-CoV-2 in cells of the respiratory system." (PMID 34887838, 2021). "Here, we identified the antiviral peptide 8P9R with dual functions to inhibit viral infection by cross-linking viruses to reduce viral entry on cell surface (i.e., TMPRSS2-mediated entry pathway for SARS-CoV) and by interfering endosomal acidification to block viral entry through endocytic pathway." (PMID 33750821, 2021). "A tentative hypothesis to explain these findings is the role of angiotensin-converting enzyme 2 (ACE2) and serine protease TMPRSS2 involved in viral infection." (PMID 32936429, 2021). "Indeed, the comparison with other viral pneumonias is pathophysiologically appropriate given that patients with DS are more prone to viral diseases that use the ACE-2-receptor/TMPRSS2 for cell binding/cell entry." (PMID 34442043, 2021). "It has been suggested that oral and respiratory tract microbiota could similarly express enzymes such as the transmembrane serine protease 2 (TMPRSS2), which may enhance viral entry into host cells and further viral infection." (PMID 34643448, 2021).